MAOA (monoamine oxidase A)
Diseases named in the same sentence as MAOA in open-access papers (continued):
Sharing a sentence is not in itself a finding about the gene and the disease.
prostate carcinoma (continued). "Recently, the overexpression of MAOA has been reported in various cancers, such as prostate cancer, renal cell carcinoma, classical Hodgkin lymphomas, and glioma." (PMID 32931665, 2020). "In prostate cancer, MAOA induced EMT and stabilized the expression of HIF-1α protein, ultimately promoting the growth, invasion, and metastasis." (PMID 32792865, 2020). "MAOA was reported to highly express in prostate cancer, classical hodgkin's lymphoma, and breast cancer tissues, but a lower expression of MAOA was found in liver cancer, pancreatic ductal adenocarcinoma, and cholangiocarcinoma 15, 18-22." (PMID 32792865, 2020). "In contrast, the oncogenic roles of MAOA in promoting the epithelial-to-mesenchymal transition (EMT) process were reported in prostate cancer." (PMID 32316576, 2020). "Liao etal demonstrated that MAOA promoted prostate tumor cell proliferation by mediating AKT phosphorylation and that MAOA absence hampered the progression of prostate cancer." (PMID 32931665, 2020). "On the other hand, high expression of MAOA in human tissues correlates with poor prognostic in prostate cancer patients and increased tumor metastasis in xenograft mouse model of prostate cancer via HIF1-α/VEGF-A/FOXO1/TWIST1 signaling pathway." (PMID 29334991, 2018). "CAFs were determined to induce EMT and invasion through a monoamine oxidase A (MAOA)/mTOR/HIF-1alpha signaling pathway in prostate cancer cells." (PMID 28611316, 2017). "A very similar function for MAOA in prostate cancer has been recently suggested by Wu and co-workers." (PMID 26689994, 2016). "To confirm the microarray findings, we used qRT-PCR to assess MAOA transcripts in microdissected prostate cancers from the same patient before and after chemotherapy." (PMID 25198178, 2014). "In vitro studies confirmed that docetaxel exposure increased the expression of MAOA in multiple prostate cancer cell lines, and inhibition of MAOA enzymatic activity using MAOA inhibitors enhanced the cytotoxicity of docetaxel." (PMID 25198178, 2014). "Subsequent studies demonstrated that MAOA inhibits prostate cell differentiation, and the MAOA inhibitor clorgyline is capable of suppressing pro-oncogenic programs in prostate cancer cells." (PMID 25198178, 2014). "MAOA inhibitors such as clorgyline and phenelzine have demonstrated the ability to slow tumor progression in prostate cancer models and may restore sensitivity to enzalutamide." (PMID 40666095, 2025). "Monoamine oxidase A (MAOA) also plays an important role in prostate cancer bone metastasis." (PMID 38464516, 2024). "Considering previous studies and our results, we suggest that MAOA inhibitors might have a special efficacy on FOXA1 mutant prostate cancer compared to the control group." (PMID 37958805, 2023). "MAOA promoted prostate cancer progression by increasing cell growth and cancer stem cells, which suggested that MAOA might be a potential therapeutic target for the treatment of prostate cancer." (PMID 36915111, 2023). "Phenelzine inhibited prostate cancer cells via inhibition of monoamine oxidase A (MAOA) which is an androgen regulated enzyme that may facilitate growth of PTEN-dependent prostate cancer." (PMID 35719960, 2022). "Furthermore, multiple studies have established the importance of increased MAOA expression in facilitating prostate cancer proliferation." (PMID 33513133, 2021). "We were particularly interested in identifying any transcription factors uniquely enriched in MED19 LNCaP cells under androgen deprivation, that correlated with MED19 occupancy, and would have an established connection to prostate cancer and regulation of MAOA." (PMID 33513133, 2021). "MAOA is overexpressed in the transition from breast cancer bone metastatic dormancy to relapse and is required for breast tumor‐initiating cells and promotes prostate cancer metastasis." (PMID 34378323, 2021). "Increased MAOA expression has been shown to correlate with prostate cancer progression." (PMID 34141613, 2021).
prostate carcinoma (continued). "The expression of MAOA has been shown to increase in various cancers, including prostate cancer and glioma, although the biological role of MAOA in cancer progression is unknown." (PMID 32616892, 2020). "Taken together, these data suggest that a combination of the MAOA inhibitor INH with tumor-targeting heptamethine cyanine dyes may prove to be a highly promising tool for the treatment of advanced prostate cancer." (PMID 30974737, 2019). "To assess whether MAOA may contribute to therapy resistance in disseminated tumor cells, we evaluated MAOA protein expression in prostate cancer metastasis acquired from 44 men with advanced castration resistant prostate cancer." (PMID 25198178, 2014). "Additionally, MAOA has been extensively studied in prostate cancer (PCa) and plays a critical role in nearly every stage, including castration-resistant prostate cancer, neuroendocrine prostate cancer, metastasis, drug resistance, stemness, and perineural invasion." (PMID 39010072, 2024). "Inhibition of MAOA in cells may exert antitumour activity in the treatment of prostate cancer." (PMID 38500079, 2024). "Monoamine oxidase A (MAOA), a mitochondrial enzyme degrading biogenic and dietary amines, has been studied in the contexts of neuropsychiatry and neurological disorders for decades, but its importance in oncology, as best exemplified in prostate cancer (PC) to date, was only realized recently." (PMID 36860320, 2023). "It was confirmed that MAOA may promote the progression of prostate cancer by mediating EMT." (PMID 32391058, 2020). "Thus, further investigations into MAOA-mediated therapy resistance mechanisms should seek to determine if the primary effects of MAOA inhibition on prostate cancer treatment responses operate through HIF1α versus other ROS-dependent or ROS-independent pathways." (PMID 25198178, 2014). "Curcumin blocks prostate carcinoma cell invasion and EMT that induced by CAFs and reduce the generation of ROS by inhibiting the monoamine oxidase A (MAOA) /mammalian target of rapamycin (mTOR)/hypoxia-inducible factor-1α (HIF-1α) signaling." (PMID 37191432, 2023). "Strikingly, MED19 upregulates expression of monoamine oxidase A (MAOA), a factor that promotes prostate cancer growth." (PMID 33513133, 2021). "Our previous work has shown that monoamine oxidase A (MAO A) is overexpressed in glioma and prostate cancer." (PMID 34679383, 2021). "Also, in 2022, a novel phthalocyanine-based photosensitizer, ZnPc-MLB, was rationally designed to target monoamine oxidase A (MAO-A), an enzyme known to be overexpressed in prostate cancer." (PMID 40807472, 2025). "Recently, in prostate cancer, MAOA was reported to stabilize HIF-1α and mediate hypoxia by increasing ROS that can repress PHD activity, thereby enhancing the growth, invasion, and metastasis of prostate cancer cells." (PMID 32792865, 2020). "Recently, several studies reported that upregulation of MAOA could promote the EMT through the accumulation of oxidative stress and induction of hypoxia in prostate cancer cells." (PMID 32316576, 2020). "A recent study discovered that MAOA (monoamine oxidase A) in stromal cells promotes their myCAF conversion, and MAOA inhibition prevented intracellular ROS accumulation, boosting WNT5A secretion to enhance the Ca2+-NFATC1 pathway in CD8 + T-cells, thus suppressing prostate cancer growth." (PMID 40847302, 2025). "Monoamine oxidase A (MAO-A), a mitochondrial enzyme that degrades monoamines including neurotransmitters, is highly expressed in basal cells of the normal human prostatic epithelium and in poorly differentiated (Gleason grades 4 and 5), aggressive prostate cancer (PCa)." (PMID 19691856, 2009). "Notably, as most of the approved drugs targeting MAOA and KDM1A were monoamine inhibitors used for mental illness or diabetes, we suggest they have a potential to cure FOXA1 mutant primary prostate cancer without lethal side effects." (PMID 37958805, 2023).
Parkinson disease (53 papers, 2011 to 2025). A progressive degenerative disorder of the central nervous system characterized by loss of dopamine producing neurons in the substantia nigra and the presence of Lewy bodies in the substantia nigra and locus coeruleus. "Monoamine oxidase A density in healthy humans and striatal dopamine synthesis in patients with Parkinson's disease are also higher in fall and winter compared with spring and summer." (PMID 33361461, 2021). "Flavonoids of several classes are inhibitors of monoamine oxidase A or B, thereby working as anti-depressants or to improve the conditions of Parkinson’s patients." (PMID 21311414, 2011). "Inhibition of MAO-A (monoamine oxidase-A), an enzyme that catalyzes oxidative deamination of neuroamines, such as dopamine, norepinephrine, and serotonin (5-HT), is a putative approach to raise the brain 5-HT level, thus alleviating the symptoms of Parkinsonism." (PMID 32630301, 2020). "Additionally, GNR-E extract exhibited a stronger inhibitory activity toward monoamine oxidase-B (MAO-B) than monoamine oxidase-A (MAO-A), suggesting its potential relevance to dopaminergic regulation, cognitive impairment and Parkinson’s disease." (PMID 41375361, 2025). "Some studies suggest a possible link between non-motor Parkinson’s symptoms and MAOA, but the results are not conclusive." (PMID 40807329, 2025). "With regard to MAOA in Parkinson’s disease, the reports of MAOA activities were problematic, variable, and somewhat inconsistent, but the observations revealed surprisingly no decreased concentrations of brain MAOA in Parkinson’s disease." (PMID 39339333, 2024).
mental disorder (43 papers, 2008 to 2025). A disease that has its basis in the disruption of mental process. "MAOA and MAOB specifically oxidize and inactivate monoamine transmitters, and MAOA gene polymorphisms were associated with susceptibility to METH-induced mental disorders." (PMID 35422687, 2022). "The first cluster contained only 3 genes including 5-HTT, SLC6A4, and MAOA, which were associated with 14 mental disorders." (PMID 31626105, 2019). "Monoamine oxidase‐A (MAOA) metabolises monoamines and is implicated in the pathophysiology of psychiatric disorders." (PMID 29667298, 2019). "Robust evidence shows that MAOA genotype moderates the association between maltreatment and mental disorders, and recent evidence shows associations between MAOA methylation and mental disorders." (PMID 29600412, 2018). "Given the potential importance of X-chromosome inactivation in the regulation of MAOA in women, its impact will be important to elucidate in subsequent epigenetic studies examining associations of abuse and mental disorders." (PMID 29600412, 2018). "Childhood physical abuse (PA) and sexual abuse (SA) interact with monoamine oxidase A (MAOA) gene polymorphism to modify risk for mental disorders." (PMID 29600412, 2018). "The first association of the MAOA gene with psychiatric disease was reported in a study of a large family in Holland; all the affected males showed characteristically abnormal behavior: aggression and sometimes violence." (PMID 18501009, 2008). "Our results, along with the previous evidence, highlight the importance of epigenetic regulation of this region of MAOA for furthering understanding of mechanisms underlying several different mental disorders that appear to depend, to some extent, on type of adversity or trauma experienced." (PMID 29600412, 2018). "We also analyzed the variation in the haplotype of the MAOA promoter in the general population to determine common haplotypes that may be used for further stratification of the genetic risk of MAOA polymorphism in psychiatric disorders." (PMID 29542091, 2018). "The literature seeks to understand MAO's etiological role and impact on mental disorders, including how the MAOA gene's genetic and epigenetic process influences the individual." (PMID 37533936, 2023). "The gene–environment effects within psychiatric disorders have been described for many genes, such as monoamine oxidase A (MAOA), the serotonin transporter (HTT), COMT, the corticotrophin-releasing hormone receptor 1 gene, and the dopamine transporter." (PMID 33924016, 2021). "Methylation of the MAOA exon I/intron I promoter region has been investigated in a myriad of psychiatric disorders, among them anxiety disorders, depression, posttraumatic stress disorder, antisocial personality disorder, and borderline personality disorder." (PMID 34421667, 2021). "These biogenic monoamines are highly relevant in the pathogenesis of psychiatric disorders and MAOA contributes to their degradation by means of oxidative deamination." (PMID 34421667, 2021). "The MAOA gene, located on the X chromosome (Xp11.23), has emerged as an important genetic factor in relation to mental illness." (PMID 32499684, 2020). "Cluster analysis showed that 5-HTT, SLC6A4, and MAOA are common genetic factors in most mental disorders; the intra-group genes in each cluster were highly correlated." (PMID 31626105, 2019). "Previous studies have showed associations of serotonin transporter (5-HTT) and monoamine oxidase A (MAOA) with behavioral and psychiatric disorders." (PMID 30126429, 2018). "Thus, disrupted monoaminergic systems can lead to impairments in brain function and mental illness, making mao−/− fish a promising tool to study the roles of MAOA/B and monoamines during brain development." (PMID 34881779, 2022). "Monoamine oxidase A (MAOA) has been related to many mental illnesses." (PMID 32499684, 2020). "Dysregulation of monoamine oxidase A (MAO-A) is observed in stress-related psychiatric disorders." (PMID 30687104, 2018).
mental disorder (continued). "The gender effect of MAOA in various psychiatric diseases has been discussed for a long while." (PMID 18501009, 2008). "Deficient expression of MAOA occurs early in life leading to inhibited outgrowth of the serotonergic system and low basal serotonin levels, that when impacted by negative environmental factors later in life promote mental disorders." (PMID 29600412, 2018). "Furthermore, epigenetic regulatory mechanisms, such as methylation and incomplete X inactivation, as well as regulation by Y-encoded transcription factor SRY could contribute to sex differences of MAOA-related psychiatric disorders." (PMID 29075213, 2017). "Early-life stress may also impact methylation of other genes related to the pathophysiology of various mental disorders, such as BDNF, COMT, MAOA, FKBP5, and SLC6A4." (PMID 33284958, 2021). "Furthermore, three active ingredients, ATR3, ATR15, and ATR102, were shown to interact with MAOA, MAOB, and NOS3, which are related to inflammation and play a role in the pathogenesis and symptoms of mental disorders." (PMID 32802132, 2020). "In terms of the associations of 5-HTTLPR and MAOA-uVNTR with behavioral and psychiatric disorders in previous studies, it would be of interest to examine the association between 5-HTTLPR or MAOA-uVNTR and ODD, which, to our best knowledge, has not been investigated." (PMID 30126429, 2018).
alcoholism (24 papers, 1995 to 2025). "The rs1137070 polymorphism of monoamine oxidase A (MAOA) is associated with alcoholism and smoking behavior." (PMID 28345608, 2017). "Frequency of genotypes of the polymorphism uVNTR of the MAOA gene in patients with alcohol dependence (AD) and in controls." (PMID 25809512, 2015). "Frequency of genotypes of the polymorphism uVNTR of the MAOA gene in patients with alcohol dependence (AD) with Lesch type I and in controls." (PMID 25809512, 2015). "Frequency of genotypes of the polymorphism uVNTR of the MAOA gene in patients with alcohol dependence (AD) with Lesch type III and in controls." (PMID 25809512, 2015). "The results of several recent studies on the association between alcohol dependence and the MAOA polymorphism, are conflicting." (PMID 25809512, 2015). "Frequency of genotypes of the polymorphism uVNTR of the MAOA gene in patients with alcohol dependence (AD) with Lesch type IV and in controls." (PMID 25809512, 2015). "Frequency of genotypes of the polymorphism uVNTR of the MAOA gene in patients with alcohol dependence (AD) with Lesch type II and in controls." (PMID 25809512, 2015). "Polymorphisms in MAOA gene have been associated with aggression, affective disorders, alcoholism and attention deficit hyperactivity disorder (ADHD)." (PMID 20976142, 2010). "A higher methylation of MAOA has been found associated with nicotine- and alcohol-dependence in women whereas a down-regulation of MAOA transcription has been reported in several cancers including lung cancer." (PMID 19956754, 2009). "A similar study on alcoholism in women from 2008 examined the association between SLC6A4 polymorphism and monoamine oxidase A promoter polymorphism (MAOA-VNTR) and severe cases of alcoholism in women." (PMID 40422201, 2025). "Especially, alcoholism (hsa05034) pathway exhibits the highest number of target connections (degree = 12), which includes consequential target genes such as MAOA, GRIN2A, GRIN2B, and CALM1." (PMID 32182911, 2020). "MAOA polymorphisms have been associated with CSF HVA concentrations in patients with atypical depression, alcohol dependence and controls as well as in a mixed group of psychiatric patients." (PMID 25073638, 2014). "They tested whether MAOA-LPR influences the impact of CSA on alcoholism and antisocial personality disorder (ASPD) in a sample of 291 women, 50% of whom had experienced CSA." (PMID 30542299, 2018). "A genetic variation in a variable nucleotide repeat (VNTR) located immediately upstream of the MAOA minimal central promoter has been already associated with different vulnerability to ASPD and two forms of SUD: alcohol dependence (AD) and nicotine dependence (ND)." (PMID 25809512, 2015). "This is illustrated by a recent report suggesting that altered DNA methylation of the regulatory region of a gene encoding the enzyme monoamine oxidase A (MAOA) in white blood cells known as lymphoblasts is associated with alcohol dependence in female but not in male subjects." (PMID 23580038, 2011). "The protective effect of the ADH1B*2 allele against alcoholism vanished in antisocial alcoholics, and the protective effect of the ALDH2*2 allele might disappear in individuals with antisocial personality disorder (ASPD) and carrying the MAOA-uVNTR 4-repeat allele." (PMID 22550993, 2012).